VIM (vimentin)
Diseases named in the same sentence as VIM in open-access papers (continued):
Sharing a sentence is not in itself a finding about the gene and the disease.
breast carcinoma (continued). "Forced expression of Tead2 in Py2 T murine breast cancer cells decreased the expression of E-cadherin and ZO-1, while increasing the levels of vimentin, ZEB1, ZEB2 and SNAI2 and altering the cytoskeleton from cortical actin-to-actin stress fibers." (PMID 32998363, 2020). "The expression levels of E-cadherin and vimentin were reduced in chemerin-treated breast cancer cells." (PMID 32325994, 2020). "Originally, AXL was identified as a downstream target of EMT in breast cancer, whereby vimentin was shown to upregulate Slug and ultimately AXL." (PMID 32148495, 2020). "Our results have shown that different EMT phenotypes of CTCs (epithelial, epithelial-mesenchymal and mesenchymal) can be distinguished in CTCs-EBF of early breast cancer using a panel of 7 genes (MGB1/HER2/CK19/CDH1/CDH2/VIM/PLS3) tested in qPCR." (PMID 30634453, 2019). "Many basic and clinical studies have found Vimentin to be a poor prognostic biomarker for breast cancer." (PMID 31182056, 2019). "IHC staining results showed that E‐cadherin protein was up‐regulated and Pygo2 protein and vimentin protein were down‐regulated in breast cancer tumour tissues treated with miR‐516a‐3p angomir." (PMID 31273950, 2019). "We next prompted an investigation of the relevance between RNF208 and Vimentin expression in patients with breast cancer." (PMID 31862882, 2019). "We selected a series of epithelial (panCK/CK18/ZO-1/E-cad) and mesenchymal marker (N-cad/Vimentin) markers which were first confirmed across breast cancer cell lines." (PMID 31527416, 2019). "Based on these findings, we supposed that MAP2K4 promotes migration and invasion of breast cancer cells by interacting with Vimentin." (PMID 31761784, 2019). "In MDA-MB-231 breast cancer cells, the structural disorder of vimentin networks occurs in the form of compact aggregation closely related to the nucleus on the RPM." (PMID 31073526, 2019). "Adipocyte-CM treated breast cancer cells upregulated the levels of mesenchymal markers (Vimentin and Zeb1) and downregulated epithelial marker (E-cadherin) indicating that adipocyte CM can promote EMT." (PMID 31383893, 2019). "We next examined the expression of E-cadherin and vimentin in breast cancer clinical samples and observed similar results." (PMID 31462314, 2019). "SPC induced phosphorylation of S71 in vimentin, leading to a reorganization of vimentin filaments of MDA-MB-435S human breast cancer cells." (PMID 31683697, 2019). "For invasion and migration analysis, Vimentin-suppressing breast cancer cells and control parental lines were cultured in Transwells and Boyden Chambers." (PMID 31761784, 2019). "Based on the invasion and migration assay results, we examined EMT signals in MAP2K4-overexpressing breast cancer cells and observed that N-cadherin, Vimentin, and Slug were significantly elevated while E-cadherin was decreased, as we expected." (PMID 31761784, 2019). "The present study explored relationship between SHH/GLI1 axis and EMT (Ecadherin, Vimentin and Snail) markers in Pakistani breast cancer cohort." (PMID 31036836, 2019). "Vimentin is one of the major members of intermediate filament family and frequently overexpresses in a variety of cancer cells such as prostate cancer, breast cancer and lung cancer." (PMID 31137656, 2019). "For example, a previous study has detected high levels of vimentin in adriamycin and vinblastine resistant breast cancer cell lines." (PMID 31579438, 2019). "In our study, MAP2K4 and Vimentin co-expression is confirmed to be an unfavorable factor in breast cancer." (PMID 31761784, 2019). "In contrast, the more mesenchymal breast cancer cell lines (E-cadherin-low and vimentin-high) were characterized by a weak DDR1 level, a high MT1-MMP, and a low BIK expression." (PMID 31130862, 2019). "The results of the present study indicated that OA inhibited the EMT formation in breast cancer cells by upregulation of E-cadherin levels and downregulation of N-cadherin and Vimentin levels." (PMID 31341911, 2019).
breast carcinoma (continued). "Transiently transfecting with siRNA to inhibit Vimentin expression in MAP2K4-overexpressing breast cancer cells reduced cell proliferation by MTT and EdU incorporation assays as well as inhibited G1 to S cell-cycle transition." (PMID 31761784, 2019). "Correlation between the clinicopathologic characteristics and MAP2K4 and Vimentin co-expression patterns in breast cancer." (PMID 31761784, 2019). "We determined mRNA levels of EMT markers (E-cadherin, N-cadherin and Vimentin) in two breast carcinoma cell lines and their chemotherapy resistant sublines by a real time RT-PCR." (PMID 31097752, 2019). "To explore the clinical prognostic value of MAP2K4 in breast cancer, we examined MAP2K4 and Vimentin expression levels in breast cancer tissues and analyzed the correlations between the expression of these markers and the clinicopathologic parameters." (PMID 31761784, 2019). "LA also regulated E-cadherin and vimentin production, suppressing invasion and migration to block breast cancer cell metastasis through regulation of the MAPK and AKT signaling pathways in MDA-MB-231 cells." (PMID 30841634, 2019). "Several studies have reported that Vimentin is overexpressed in a large number of cancers including breast cancer." (PMID 31244288, 2019). "Similar alternative usage of the gene promoter and first exon has been also observed for human VIM gene in breast cancer and adrenal carcinoma cell lines, but the functional properties of these transcripts are still unclear." (PMID 32009982, 2019). "Matrix metalloproteinase (MMP) family such as MMP2 and MMP9, the vital epithelial-mesenchymal transition (EMT)-related factor vimentin, and the actin-bundling protein fascin play essential roles in breast cancer metastasis." (PMID 31186039, 2019). "Wi-A was shown to induce vimentin aggregation, inhibiting invasion and metastases of the breast cancer cells." (PMID 31757995, 2019). "Aberrant expression of Vimentin is restricted to TNBC cells among the breast cancer cells and is involved in a mesenchymal phenotype, aggravating the invasive potential of breast cancer cells." (PMID 31862882, 2019). "Vimentin expression was found to be increased and E-cadherin expression was found to be decreased in breast cancer cells by the effects of CAF-educated monocytes." (PMID 30816272, 2019). "Depleting vimentin expression through shRNA resulted in reduced population of breast cancer stem cells, as measured by high expression of aldehyde dehydrogenase, suggesting that vimentin is required for the maintenance of breast cancer stem cells." (PMID 31126068, 2019). "In particular, miR-21, MMP1, MMP9, MMP13, CXCR4 and vimentin were found overexpressed in the invasive margins of breast cancer tissues of clinical samples and in the cancer cell lines; E-Cadherin, on the other hand, was decreased." (PMID 31362429, 2019). "Silencing SCUBE2 triggered the acceleration of the E-cadherin and the decrease of the vimentin in breast cancer cells." (PMID 31404982, 2019). "This is already a reality for colorectal and breast cancer: the identification of vimentin gene DNA methylation in blood samples and the PTIX2 gene in breast cancer are two representative examples." (PMID 31554341, 2019). "Regarding the mechanism of action, our study also was the first to show that MAP2K4 overexpression activates the PI3K/AKT pathway and interacts with Vimentin in breast cancer cells." (PMID 31761784, 2019). "Some studies, including some breast-cancer studies show increased VIM expression correlates with cisplatin resistance." (PMID 31684899, 2019). "For example, EMT induction by snail or twist overexpression promoted the generation of cancer stem cells in human mammary epithelial cells, and markers of mesenchymal cells, including vimentin, was high in CD44high/CD24low stem cells of breast cancer." (PMID 31126068, 2019).
breast carcinoma (continued). "In a previous study, we have examined this correlation in multiple breast cancer cell lines, by analyzing expression levels of E-cadherin, vimentin, DDR1, DDR2, MT1-MMP, and BIK mRNAs in 58 breast cancer cell lines." (PMID 31130862, 2019). "The Spearman’s test showed that MAP2K4 expression was positively correlated with Vimentin expression in the breast cancer patients (γ=0.753, P<0.001)." (PMID 31761784, 2019). "In the current study, we also detected that knockdown of SNX27 significantly suppressed the expression of Vimentin in breast cancer cells." (PMID 31182056, 2019). "As just described, it has reported that melatonin decreases E-cadherin and increases vimentin and N-cadherin expression in both canine and human mammary tumour cells (CMT-U229 and MCF7 respectively), inducing an anti-invasive effect in these cells." (PMID 31684950, 2019). "For the human dataset, vimentin expression was found to be variable across four TNBC PDX mammary tumors at the RNA level." (PMID 30841919, 2019). "Then, we simultaneously overexpressed ER and knocked down CRABP2 in ER− mammary cancer cell lines, and found that E-cadherin expression increased and ZO-1 and Vimentin expression changed a little when compared with the overexpressed ER group." (PMID 31419991, 2019). "Fibronectin affects other markers of EMT in breast cancer cells, upregulating the expression of N-cadherin, Snail, vimentin, and MMP-2." (PMID 30487436, 2018). "Previous studies showed that knockdown of CLCA4 expression caused downregulation of E-cadherin and upregulated the expression of N-cadherin and vimentin in breast cancer cells." (PMID 30312171, 2018). "In MDA-MB-231 breast cancer cells, knockdown of β -catenin led to an increase in cell mobility and in mesenchymal vimentin expression, which suggested an EMT." (PMID 29435153, 2018). "On the contrary, keratin 13 expression was decreasing after knockdown of vimentin in breast cancer cell lines." (PMID 30005669, 2018). "IL-6, secreted from stromal cells including tumor-associated macrophages and T cells, can promote EMT in breast cancer cells, with the induction of vimentin, N-cadherin, Snail, and Twist." (PMID 30487436, 2018). "Our results showed that breast cancer cells co-cultured with human adipocytes had a decreased expression of E-cadherin and an increased expression of vimentin which are key markers for EMT." (PMID 29891854, 2018). "Breast cancer has also been reported to be related to overexpression of vimentin, with correlation with increased invasive behaviour and promotion of migration of mammary epithelial cells." (PMID 30248895, 2018). "As expected, we observed a significant increase of TGFβ and vimentin expression in breast cancer tissues with higher amount of BOLCs." (PMID 30327566, 2018). "Vimentin expression was also inversely correlated with CEACAM5 expression in a panel of breast cancer cell lines." (PMID 29736411, 2018). "Collectively LSD1 modulates breast cancer EMT, colocalises with the key EMT-TF Snail, and regulates the expression of several hallmark EMT proteins including E-cadherin and vimentin." (PMID 29311580, 2018). "As expected, all ER+ breast cancer cells expressed higher levels of E-cadherin with undetectable vimentin." (PMID 29930294, 2018). "This is the very first report for such effect of resistin in ovarian cancer cells, even though resistin was earlier reported to increase invasion, and the mesenchymal marker vimentin in breast cancer cells." (PMID 30131543, 2018). "Vimentin is overexpressed in several aggressive breast cancer cell lines and correlated with increased tumor cell migration and invasion." (PMID 28562350, 2017). "Linear regression analysis of clinical breast cancer specimens showed a positive correlation between p62 and vimentin protein expression." (PMID 28968743, 2017).
breast carcinoma (continued). "Whereas vimentin concentration averaged 1462.63 ± 175.23 ng/ml in breast cancer patients and 851.29 ± 109.04 ng/ml in controls, DAPK1 concentration averaged 1105.75 ± 396.56 ng/ml and 371.09 ± 119.82 ng/ml in breast cancer patients and controls, respectively." (PMID 28616237, 2017). "In human cancers, aberrant methylation of VIM has been shown in colorectal cancer, gastric cancer, bladder cancer, pancreatic cancer, cervical cancer and breast cancer." (PMID 28333958, 2017). "On the other hand, lumican treatment of shERβΜDA-MB-231 breast cancer cells revealed a slight increase of the expression levels of the epithelial marker E-cadherin, whereas it decreased that of the mesenchymal marker vimentin." (PMID 28332606, 2017). "The mean serum concentration of the breast cancer patients and the controls were 1800 pg/ml and 897 pg/ml respectively for vimentin and 1105 pg/ml and 372 pg/ml respectively, for DAPK1." (PMID 28616237, 2017). "Employing ELISA, we assayed for vimentin and death-associated protein kinase 1 (DAPK1) from thawed archived (stored at -80 °C) serum samples obtained from 40 clinically confirmed Ghanaian breast cancer patients and 40 apparently healthy controls." (PMID 28616237, 2017). "Insufficient MWA induced EMT-like changes of residual breast cancer by down-regulation of E-cadherin and up-regulation of vimentin and N-cadherin in vitro and in vivo." (PMID 29383144, 2017). "PLK1 phosphorylates vimentin on S82, which regulates cell surface levels of β1 integrin and thereby promotes the invasiveness of breast cancer cells." (PMID 28953239, 2017). "On the part of vimentin, earlier reports suggest that there is elevated expression of the protein in breast cancer cell lines and tissues and also in several aggressive breast cancer cell lines." (PMID 28616237, 2017). "This “inside-out” signaling has been reported in breast cancer cells by which Ras up-regulates vimentin and then transcriptionally activates receptor tyrosine kinase Axl to induce tumor migration and invasion." (PMID 28841878, 2017). "This work reports on two proteins, vimentin and Death Associated Protein Kinase 1 (DAPK1) as targets for predicting tumour aggression in breast cancer development and progression." (PMID 28616237, 2017). "Breast carcinoma biopsies were immunolabeled for cytokeratin (CK) and vimentin (vim) to distinguish breast carcinoma cells from stromal cells, respectively." (PMID 28129640, 2017). "Basal markers α-smooth muscle actin, calponin, vimentin, and p63 that were expressed by CMT-U309 have been mostly associated with poor prognosis in human breast cancers." (PMID 28955712, 2017). "EMT is an important process in cancer progression and metastasis, and AXL is an inducer of EMT-related proteins, such as N-cadherin, Snail, Slug, and vimentin in breast cancer cells." (PMID 29259259, 2017). "Vimentin overexpression, on the other hand, is a marker of epithelial to mesenchymal transition in cancers of epithelial origin, like breast cancer." (PMID 28910304, 2017). "The vimentin-ERK axis promotes EMT of cell metastasis of breast cancer cells by regulating Slug phosphorylation." (PMID 28402270, 2017). "All cells obtained from breast cancer specimens and normal tissue, as expected, expressed only vimentin." (PMID 28596490, 2017). "In order to test if vimentin acted as an important mediator in p62 promoting breast cancer cells invasion, we overexpressed vimentin in both MDA-MB-231-shNC and MDA-MB-231-shp62 cells." (PMID 28968743, 2017). "Vimentin protein expression was downregulated upon p62 suppression and upregulated with p62 overexpression in breast cancer cells." (PMID 28968743, 2017). "Pearson's correlation analysis run on 226 samples made up of 56 breast cancer cells showed that the FRK transcript levels negatively correlated with the transcript levels of VIM, CDH2, and TWIST1, with R-values of -0.28; -0.20; -0.25 respectively (P<0.001)." (PMID 29348886, 2017).
breast carcinoma (continued). "In a recent report, EMT was shown to trigger TF expression and metastasis, and co-expression of TF and vimentin was found in subpopulation of circulating tumor cells (CTC) in metastatic breast cancer patients." (PMID 28938620, 2017). "Skalova noted in her original article that SC has a similar immunohistochemical profile to secretory breast cancer and expresses S-100 protein, mammaglobin, and vimentin." (PMID 28484662, 2017). "In the dataset of 50 breast cancer lines TF expression clustered with higher levels of basal-marker vimentin, keratin KRT5/14 and caveolin-1 (CAV1) but lower levels of luminal-marker keratin KRT8/18, ERBB3 and ESR1." (PMID 28938620, 2017). "For example, miR-30a directly targets vimentin and thereby inhibits cell migration and cell invasion in breast cancer." (PMID 29271928, 2017). "Taken together, these results demonstrate that vimentin plays an essential role in p62-mediated invasion in breast cancer cells." (PMID 28968743, 2017). "Histological analysis of both human primary breast and brain metastatic tumor samples showed the presence of vimentin-positive stromal cells surrounding cytokeratin-positive breast cancer cells." (PMID 28649646, 2017). "In summary, we demonstrate that the signalling adaptor p62 enhances breast cancer metastasis through interacting with vimentin." (PMID 28968743, 2017). "As shown, compared to other breast cancer cell lines, they share high expression levels of vimentin and undetectable E-cadherin, accordingly to their unique features of epithelial mesenchymal transition (EMT)." (PMID 28425453, 2017). "Recent reports have shown that EMT, which is characterized by the loss of epithelial markers such as E-cadherin and the induction of mesenchymal markers, including vimentin, N-cadherin, and fibronectin, plays a pivotal role in breast cancer progression." (PMID 28867761, 2017). "This is supported by previous work indicating the expression of both N-cadherin and vimentin proteins in breast cancer cells can be reduced by intracellular Ca2+ chelation and are partially regulated by Ca2+ channel TRPM7." (PMID 27793015, 2016). "On the other side, GPC3 overexpression induced the mesenchymal-epithelial transition (MET) of MDA-MB231 breast cancer cells, which re-expressed E-Cadherin and reduced the expression of vimentin and N-Cadherin." (PMID 27507057, 2016). "Earlier study has confirmed the expression of vimentin and cytokeratin in breast cancer and vimentin positivity has been commonly noticed in numerous types of cancer and was correlated with a sign of an epithelial-mesenchymal transition." (PMID 27190522, 2016). "All CaMKII overexpressing breast cancer cells had increased levels of pERK1/2 and vimentin and decreased levels of E-cadherin, and MDA-MB-231 cells also possessed elevated levels of pFAK." (PMID 27605043, 2016). "Our present miRNA study demonstrates that Slug, as well as vimentin, is a miR-30a target that is particularly important in breast cancer progression." (PMID 26918943, 2016). "The overexpression of vimentin has been reported in various tumor cell lines, including breast cancer, central nervous system tumor, prostate cancer, malignant melanoma, and lung cancer cell lines." (PMID 27713131, 2016). "The miR-30a/Slug axis inhibited filopodial assembly during EMT in breast cancer cells, which resulted in reduced levels of mesenchymal proteins, e.g., vimentin and fascin." (PMID 26918943, 2016). "Vimentin expression was significantly lower in control HNSCC cells as compared to breast cancer cells, which express high levels of vimentin." (PMID 27075696, 2016). "CDH2 (encoding N-cadherin), VIM (encoding vimentin), TWIST1/2 (products which are EMT transcriptional factors) and SNAI1, as well as ZEB1, are well known key players involved in EMT-like processes of breast cancers." (PMID 27617643, 2016).